CRP (C-reactive protein)
Diseases named in the same sentence as CRP in open-access papers (continued):
Sharing a sentence is not in itself a finding about the gene and the disease.
bacteremia (continued). "In summary, this study has found that bacteremia, CRP > 162.375 mg/L, and delayed operation time > 9.50 days are independent risk factors for DSAI secondary to OAI in children." (PMID 40437616, 2025). "After 60 h of inoculation, bacteremia reached >108 cfu/ml in all groups of mice except in mice treated with WT CRP 30 min prior to inoculation." (PMID 40740789, 2025). "Logistic regression identified the second CRP as the only independent predictor of bacteremia (adjusted odds ratio 1.09; 95% CI 1.03-1.15; p<0.05)." (PMID 40809608, 2025). "Comparing unexplained fever episodes with high CRP to those with bacteremia, 192 genes were differentially expressed." (PMID 40806258, 2025). "The second CRP not only emerged as an independent predictor of bacteremia in multivariate logistic regression but also demonstrated the highest predictive importance in random forest analysis." (PMID 40809608, 2025). "In the first-line treatment, non-effective episodes were associated with older age, heavier body weight, lower white blood cell (WBC) count, higher CRP level at entry, stem cell transplantation, and bacteremia." (PMID 40626871, 2025). "In contrast to pPCT, CRP was significantly above the reference limit (< 10.5 mg/L) in dogs with bacterial sepsis and nSIRS." (PMID 40607352, 2025). "Logistic regression, random forest analysis, and penalized regression were used to determine predictors of neonatal bacteremia, with a focus on the timing of CRP measurements." (PMID 40809608, 2025). "Our study results indicate that late CRP measurement was identified as the sole significant predictor for bacteremia in the multivariate logistic regression analysis." (PMID 40809608, 2025). "COVID-ICU patients presented more severe disease as this reflected in higher SOFA, APACHE, and PITT bacteremia scores, but also in higher CRP values." (PMID 41305390, 2025). "Despite the risk of soft tissue infection increasing bacteremia, preoperative infection control, close monitoring of PCT and CRP, and timely adjustments to antimicrobial therapy enabled successful management of postoperative infections." (PMID 40166072, 2025). "In this study, we employed CRP KO mice and investigated the effects of the amyloid-binding CRP molecules E-CRP-1 and E-CRP-2 on the survival of and bacteremia in mice when administered 12 h after inoculation." (PMID 40740789, 2025). "In tropical medicine, CRP has been explored as a means to distinguish severe malaria from bacterial sepsis and to differentiate dengue from bacterial coinfections." (PMID 41010302, 2025). "In our subgroup analysis, the abundance of CD38high monocytes showed a positive correlation with the severity of BS subgroup bacterial sepsis (e.g., CRP, APACHE II scores) and 28‐day mortality." (PMID 40145840, 2025). "It was concluded that the reliability ofnCD64 expression was higher than that of PCT and CRP in prediction of bacteremia in FN patients." (PMID 40369641, 2025). "Intestinal occludin levels showed a significant correlation with circulating CRP at day 14 (p = 0.035, r = 0.45) as well as bacteremia (p = 0.06, r = 0.40)." (PMID 41266667, 2025). "In our study, PCT performed better than serum HNL, CRP, and leucocyte count in predicting bacterial sepsis, which is in line with other studies comparing PCT to other biomarkers." (PMID 40598497, 2025). "Despite the high inter-individual variation in the timing of bacteremia peaks, we found that CRP levels in sera remained near baseline in all animals until at least 2 dpi." (PMID 40766078, 2025). "Transcriptomics revealed 266 differentially expressed genes in children with bacteremia compared to unexplained fever with low CRP levels." (PMID 40806258, 2025). "In children with bacteremia, 266 genes were differentially expressed compared to children with unexplained fever and low CRP." (PMID 40806258, 2025). "Human CRP protects against lethal pneumococcal infection by decreasing bacteremia in mouse models of the disease." (PMID 40740789, 2025).
bacteremia (continued). "Laboratory tests showed severe inflammation (white blood cell: 23.95 × 109/L; C-reactive protein: 196.06 mg/L; procalcitonin: 21.15 ng/mL) and methicillin-sensitive S. aureus bacteremia." (PMID 41327646, 2025). "In the prediction of mortality, the combination of IL-6 and CRP reached 92% sensitivity in the presence of bacteremia but specificity was relatively low at 78%." (PMID 41011807, 2025). "IL-6 showed 74% sensitivity and 49% specificity for bacteremia, with 45% positive predictive value, but correlated poorly with early CRP (r = 0.26 on day 1 vs. 0.53 on day 2)." (PMID 40647525, 2025). "Blood samples were assessed for bacteremia and C-reactive protein, and animals were monitored for body weight, body temperature, blood pressure, and clinical signs of disease throughout the study." (PMID 40766078, 2025). "On day 2 of fever onset, 134 genes distinguished children with bacteremia from unexplained fever with low CRP levels." (PMID 40806258, 2025). "Fifth, the CRP cutoff used in this study (CRP ≥10 mg/dL) was adopted from prior literature where it showed significance in relation to persistent bacteremia." (PMID 39776932, 2025). "Children with unexplained fever and high CRP had a gene expression profile distinct from those with bacteremia, including downregulated CXCL1, MYOZ3, and HSPG2." (PMID 40806258, 2025). "The DSAI group showed significantly higher CRP levels, bacteremia incidence, MRSA infections, PICU admissions, surgical delays, ≥ 2 surgeries, longer postoperative fever, prolonged hospital stays, and worse prognosis (P < 0.05)." (PMID 40437616, 2025). "After 66 h of inoculation, bacteremia reached >108 cfu/ml in all groups of mice except in mice treated with either WT CRP or E-CRP-2, 30 min prior to inoculation." (PMID 40740789, 2025). "Multivariate logistic regression showed that the second CRP was the only independent predictor of bacteremia (adjusted odds ratio 1.09; 95% CI 1.03-1.15; p<0.05)." (PMID 40809608, 2025). "Bacteremia was significantly reduced in mice treated with either CRP species 30 min prior to inoculation for the entire duration of the experiment." (PMID 40740789, 2025). "Combined data also raise the possibility that SAP cooperates with CRP in reducing bacteremia and bacterial load." (PMID 40740789, 2025). "Serial serum CRP predicted fever and bacteremia in neutropenic patients with acute leukemia in one study." (PMID 39694764, 2024). "Using the Pitt bacteremia score, leukocyte counts, and CRP responses during initial treatment can improve treatment strategies and survival for patients with SDSE." (PMID 39173664, 2024). "In bacteremia, IL-6 and IL-10 were more positive than PCT and CRP, and IL-6 and IL-10 were significantly more specific than PCT in the diagnosis of diagnostic G- bacteremia." (PMID 39559703, 2024). "The respiratory rate was significantly higher in patients with bacteremia (26 vs 29, P = .038), and C-reactive protein and procalcitonin levels were also significantly higher (53 mg/L vs 105 mg/L, P = .002 and .27 vs 1.24, P = .031, respectively)." (PMID 38770207, 2024). "Patients with bacteremia had higher mortality rates (40.9% vs. 18.3%), elevated CRP levels, and longer activated partial thromboplastin times, highlighting these as significant risk factors for bacteremia in severe dengue patients." (PMID 39677171, 2024). "We aimed to evaluate the diagnostic precision of procalcitonin (PCT), soluble urokinase plasminogen activator receptors (suPARs), and C-reactive protein (CRP) in diagnosing UTIs, grading the severity of UTIs, and ruling out bacteremia." (PMID 38542009, 2024). "The study highlighted the importance of concurrently measuring PCT and CRP for the precise detection of GN bacteremia." (PMID 38172766, 2024). "Studies have shown that NLR is more effective than C-reactive protein (CRP), leukocyte count, and lymphocyte count in determining bacteremia in infectious diseases." (PMID 39421611, 2024).
bacteremia (continued). "The mean CRP/albumin ratio (8.6 ±1.7) and mean quick Pitt bacteremia score (2.8 ±0.4) were significantly higher in patients with bloodstream infections who died during their hospitalization compared to those who survived." (PMID 39252713, 2024). "Four studies focused on the diagnostic value and the utilization of serum PCT, C-reactive protein (CRP), serum lactate, and Il-6 in predicting bacteremia in adult patients and diagnosis of bacterial sepsis." (PMID 38254218, 2024). "Complete blood count parameters and C-reactive protein levels cannot be used in ML models to predict bacteremia in newborns." (PMID 36502550, 2023). "Increasing evidence indicates that younger patients with bacteremia tend to exhibit lower Hb levels and higher CRP levels." (PMID 37628401, 2023). "ROC analysis showed that the best cut-off values for predicting bacteremia in infants with pyrexia were a BT of 38.7 °C, neutrophil count of 57.9%, and CRP concentration of 53.8 mg/L." (PMID 37679686, 2023). "Conversely, for ruling out bacteremia, neutrophil counts of 6% or lower on day 1 and CRP levels of 1.15 mg/L or lower on day 2 and of 4.6 mg/L or lower on day 3 were found to be effective." (PMID 37679686, 2023). "The authors created ML models to analyze the viability of using CBC and CRP to predict and identify early bacteremia in neonates." (PMID 36502550, 2023). "In our research, we did not incorporate data related to erythrocyte sedimentation rate (ESR) or the C-reactive protein (CRP) as predictive markers for bacteremia." (PMID 37891995, 2023). "We found that serum parameters were highly valid for diagnosing bacteremia when neutrophil counts were ≥ 83% or CRP levels were ≥ 336.5 mg/L in febrile infants." (PMID 37679686, 2023). "Independent predictors for focal infection detection were community acquisition of bacteremia with odds ratio (OR) 3.03 [95% confidence interval (CI) 1.04–8.77], p-0.042 and C reactive protein (CRP) with OR 1.09 [95% CI 1.04–1.14], p < 0.001." (PMID 37640802, 2023). "The following criteria had a sensitivity of 100% for excluding pediatric bacteremia: BT ≤ 37.7 °C, neutrophil count ≤ 6.0%, and CRP levels ≤ 1.15 mg/L." (PMID 37679686, 2023). "Procalcitonin appears to be more reliable than CRP in predicting bacteremia, but it is more expensive." (PMID 36502550, 2023). "The clinical value of NLR combined with lymphocytic reduction in the confirmation of bacteremia in an emergency is better than CRP, white blood cell count, and neutrophil count." (PMID 36927471, 2023). "Our findings revealed that the probability of bacteremia increased when the neutrophil count was higher than 83% and the CRP levels were greater than 336.5 mg/L." (PMID 37679686, 2023). "We have also observed lower Hb and higher CRP levels in children with bacteremia, urinary tract infection, or Kawasaki disease in our previous studies." (PMID 37628401, 2023). "The present study shows that ML models based on CBC and CRP cannot be used to predict neonatal bacteremia in routine clinical practice in the neonatal intensive care unit." (PMID 36502550, 2023). "In a study on bacteremia in community-acquired pneumonia, elevated CRP followed by lower plasma albumin was found to predict a higher risk of community-acquired bacteremia." (PMID 37768395, 2023). "This contrastingly substantial correlation highlights the potential clinical significance of CRP as an indicator of Hb variations in the context of bacteremia." (PMID 37628401, 2023). "In this review, very high serum concentrations of CRP (near to 1000‐fold) were found as the predictor for severe COVID‐19 condition, which were previously seen in some bacterial sepsis." (PMID 38156391, 2023). "There were higher CRP levels, lower Hb concentrations, and lower Z scores of Hb compared to the non-bacteremia group (p < 0.001, p = 0.003, p < 0.001, respectively)." (PMID 37628401, 2023).
bacteremia (continued). "Presepsin has been studied in several studies of bacterial sepsis and has been already compared to other biomarkers like C-reactive protein (CRP) and procalcitonin (PCT)." (PMID 36882572, 2023). "The level of IL-6 can guide management of children with febrile neutropenia and are more specific and sensitive than CRP in the diagnosis of bacteremia/sepsis." (PMID 35463642, 2022). "Presepsin, PCT, and CRP values were higher in the bacteremia group than the non-bacteremia group (p < 0.001)." (PMID 36072944, 2022). "In addressing RQ1, the bacteremia prediction capability of ML models and those predictions made by different biomarkers (CRP or PCT) were measured through cross-validation and testing data, and the results of the AUC were presented." (PMID 35351003, 2022). "Although our data suggest that CRP has great potential for distinguishing between candidemia and bacteremia at a cut-off of 130 mg/L (p = 0.005), its sensitivity and specificity for Candida sepsis are poor (67.2% and 66.9%, respectively; AUC = 0.67)." (PMID 35330311, 2022). "Among the biomarkers, ROC curve analysis revealed that the highest performance for predicting bacteremia was procalcitonin (AUC 0.80; 95% CI: 0.72–0.88), followed by presepsin (AUC 0.69; 95% CI 0.60–0.79), and CRP (AUC: 0.60; 95% CI 0.49–0.70)." (PMID 35778478, 2022). "At the time of detection of bacteremia, CRP was higher in 85.7% of the cases, and procalcitonin value was higher than normal in 73.5% of the cases." (PMID 36291502, 2022). "Elevated white cell count, CRP, SIRS criteria, and SOFA score are associated with complicated bacteremia." (PMID 35887987, 2022). "In order to evaluate the predictive impact of cytokines for respiratory bacterial infection and respiratory infection associated with bacteremia in NHL, we examined the body temperature, cytokine profile, PCT, and CRP of 229 newly diagnosed NHL patients." (PMID 35463642, 2022). "As CRP—an acute phase-secreted protein—was elevated during bacteremia, the correlation with bacterial load was calculated." (PMID 35925895, 2022). "Patients with bacteremia or fungemia from the follow-up dataset had the highest mean CRP and PCT levels on the first day of admission." (PMID 36555941, 2022). "After adjusting for age, sex, ICU type, bacteremia, vasopressor use, WBC, PLT, hemoglobin, ALT, CK-MB, sodium, INR, and CRP, a strong association was observed between the L/A ratio and hospital mortality (OR 1.44, 95% CI 1.31–1.59, P < 0.001)." (PMID 36539725, 2022). "The ROC curve was employed to further evaluate the diagnostic ability of body temperature, CRP, PCT, IL-6, and IL-8 in cases with respiratory bacterial infection and bacteremia." (PMID 35463642, 2022). "The ML models using only CBC/DC data yielded more accurate bacteremia predictions compared to those by methods using CRP and PCT data and reached similar prognostic performance as by PCT data." (PMID 35351003, 2022). "Given that PCT has proven to be more accurate than CRP in determining the prognosis of bacteremia, this study excluded CRP when comparing the prognoses of bacteremia." (PMID 35351003, 2022). "To fill the gaps, we developed ML models to further utilize readily existing CBC/DC data to determine the occurrence and prognosis of bacteremia using CRP and PCT." (PMID 35351003, 2022). "Adding CRP as a predictor to CBC/DC only slightly enhanced its bacteremia prediction capability (AUC = 0.814)." (PMID 35351003, 2022). "Strikingly, there were four patients with bacteremia, and, in all these patients, CRP was >100 mg/mL, while WBC values were abnormal in 3/4 (75%) of patients." (PMID 35631080, 2022). "Features in CBC/DC have even shown more accurate prediction capability than CRP in the case of bacteremia." (PMID 35351003, 2022). "Of 2200 patients with bacteremia, 460 had a low first CRP (<30 mg/L) of whom 229 were further investigated to find that they had a significant five-fold higher C-reactive protein level with their second test." (PMID 35897672, 2022).
bacteremia (continued). "With regards to laboratory indices, the maximum CRP values were higher in the persistent bacteremia group." (PMID 35740171, 2022). "RQ1How accurate are predictions of bacteremia made with ML models based on CBC/DC compared to predictions traditionally made using only CRP or PCT levels?" (PMID 35351003, 2022). "Septic distribution through spread into the blood stream (bacteremia) or cerebrospinal fluid (meningitis) can have severe consequences resulting in multiorgan failure and shock, where CRP levels are known to be high." (PMID 35160110, 2022). "An important new feature in the Gilliam-infection NHP model is the similarity of CRP dynamics to humans; the CRP levels peaking during bacteremia compares to human disease." (PMID 35925895, 2022). "The CRP showed outstanding performance for the detection of bacteremia in this study when using a cut-off value of >12.50." (PMID 35176042, 2022). "Compared to the baseline, CRP levels were markedly increased during the peak of the bacteremia; for the Gilliam group at 6 dpi, while for Karp at 12 dpi." (PMID 35925895, 2022). "Then, the model was compared to CRP and PCT in terms of bacteremia prediction for the CRP&CBC/DC group and PCT&CBC/DC group, respectively." (PMID 35351003, 2022). "In cases of persistent bacteremia and elevated CRP levels, IE is a possible diagnosis, even in extremely preterm newborns." (PMID 35455502, 2022). "CRP serum levels were determined only in the bacteremia group of patients, and they were higher than the normal range (0.8–1.0 mg/dL or lower), both on day 0 and day 7, despite their significant reduction during treatment (p = 0.0048)." (PMID 35741214, 2022). "Nevertheless, another study of critically ill cancer patient revealed that pro-ADM and PCT had similar areas under the roc curve for identifying bacteremia, both being superior to that of CRP." (PMID 33869250, 2021). "N/L seemed to be a safe, simple and promising marker in predicting bacteremia and in grading community-acquired pneumonia, and N/L was more accurate and objective than C-reactive protein." (PMID 34786313, 2021). "Adverse effects occur more frequently in patients with inflammatory bowel disease treated with FMT; Fever, increased C-reactive protein, and bacteremia have been also reported." (PMID 34721980, 2021). "We performed a diagnostic accuracy study in Burkina Faso to assess the performance of a new diagnostic algorithm–the IMS–and the well-known biomarkers CRP and PCT to detect bacteremia among febrile ≥ five years old patients in a malaria endemic setting." (PMID 33647009, 2021). "We found that the IMS had a higher diagnostic accuracy to detect bacteremia than PCT at a cut of value of 0.5 ng/ml, and was comparable in sensitivity, but superior in specificity to CRP at a cut of value of 20 mg/L." (PMID 33647009, 2021). "Based on presented evidences, it can be concluded that FCBI-index and CRP are general markers of bacterial infection whereas serum PCT is useful only in predicting bacteremia in critically ill febrile patients." (PMID 34844193, 2021). "Its sensitivity is similar to CRP using 20 mg/L as cut-off value, but it is considerably better at excluding bacteremia due to its high NPV and specificity." (PMID 33647009, 2021). "A study published in 2004 proved that PCT and IL-6 were more reliable markers than CRP in predicting bacteremia in patients with febrile neutropenic fever." (PMID 34828740, 2021). "Our results show that PCT and CRP are the most accurate routinely available predictors of bacteremia in children with CAP." (PMID 34746044, 2021). "Elevated CRP indicates activation of the immune system and is commonly used as an indicator of bacterial sepsis." (PMID 34706677, 2021). "Mice were protected, without administering human CRP, when up to 107 cfu of pneumococci were injected into mice, suggesting that endogenous murine WT CRP was sufficient to protect mice from lethality when bacteremia was relatively lower." (PMID 33117400, 2020).